VIM (vimentin)
Diseases named in the same sentence as VIM in open-access papers (continued):
Sharing a sentence is not in itself a finding about the gene and the disease.
tumor (continued). "Immunohistochemically, the tumor cells were cytokeratin -, vimentin +, CD3+, CD45RO+, CD5-, CD7-, CD4-, CD8-, CD10-, CD20-, CD30-, CD79a-, CD138-, CD56-, granzyme B-, TIA-1 cytotoxic granule-associated RNA binding protein (TIA-1) + and ALK-." (PMID 22931631, 2012). "Our data demonstrated that restoration of miR-138 significantly inhibited both mRNA and protein expression levels of VIM in RCC cells, suggesting VIM was regulated by tumor suppressive miR-138." (PMID 22766839, 2012). "Research suggests that vimentin, a major intermediate filament (IF) protein of mesenchymal cells, is very important for tumour growth and metastasis." (PMID 23116199, 2012). "IHC studies have shown that the tumor cells in DFSP contain vimentin and actin (focally and inconstantly) and CD34 (strongly and consistently), but they are negative for S100 protein, HMB-45, keratin, and FXIIIa." (PMID 23316399, 2012). "Cytokeratin negativity and vimentin positivity confirmed the malignant mesenchymal nature of the tumor in the present case." (PMID 23119211, 2012). "Immunohistochemically, the tumor cells showed typically positive for Vimentin(27/27), CD68(13/13), and MAC387(2/2), and AAT(13/14), Lysozyme(11/12), ACT(10/12) showed positive in most cases." (PMID 22221822, 2012). "Levels of HIF-1α, N-cadherin, and vimentin were upregulated in tumor cells, and E-cadherin was downregulated, under conditions of hypoxia." (PMID 23137165, 2012). "To determine if Pan02 cells have undergone EMT, we stained tumor sections with E-cadherin, an epithelial marker, and vimentin, a mesenchymal marker." (PMID 22348081, 2012). "Although the expression concerned a limited percentage of neoplastic cells in some tumours, vimentin was significantly related to postsurgical survival." (PMID 21448168, 2011). "The two components of the tumour were confirmed using the immunohistochemical staining (cytokeratin and vimentin)." (PMID 22203850, 2011). "The TGF-β1, NF-κB p105, fascin, Par-6α, PKC-ζ and vimentin, showed expression in the cytoplasm of tumor cells while E-cadherin demonstrated focal membrane-associated and/or cytoplasmic positivity in a minority of the tumors." (PMID 21390241, 2011). "A significant association was observed between GSTPi-positive, vimentin-positive and α-SMA-positive fibroblast in tumour microenvironment at both sites." (PMID 21897388, 2011). "In this model, high (>10%) tumour epithelial vimentin expression was a more powerful predictor of outcome than the N TNM stage, the type of surgery, and tumour size, the risk of death being 1.53." (PMID 21448168, 2011). "Immunohistochemically, the tumor cells are diffusely positive for vimentin and focally for epithelial membrane antigen (EMA)." (PMID 22567356, 2011). "All OTBCs exhibited a complete loss of epithelial markers associated with tumor suppressive functions, such as E-cadherin (CDH1) and Maspin, and a gain of mesenchymal markers, such as VIM and neural cell adhesion molecule (N-CAM)." (PMID 21952072, 2011). "An analysis of the immunohistochemical profile of the tumor cells showed positivity for vimentin, S-100 protein, and glial fibrillary acidic protein (GFAP), but not for smooth muscle actin (α-SMA) and cytokeratin 14 (CK14)." (PMID 22152025, 2011). "Vimentin expression was induced under hypoxic conditions and corresponded to increases in invasive metastatic potential of LNCaP tumor cells." (PMID 24212937, 2011). "Immunohistochemically, the tumor cells are diffusely positive for vimentin and focally for CD68 and CD34." (PMID 22567356, 2011). "Immunohistochemically, the tumor cells are diffusely positive for vimentin and occasionally for muscle specific actin and α-smooth muscle actin, suggestive of focal myofibroblastic differentiation." (PMID 22567356, 2011). "The tumor also expresscs Vimentin, PGP9.5, NKI/C3, and CD68 while some markers such as Inhibin-α, Calretinin, Galectin-3, and HBME show varying rates of staining." (PMID 22132340, 2011).
tumor (continued). "Immunohistochemically, the tumor cells showed strong vimentin immunostaining in all three cases and were positive for CD34 in two cases but negative for EMA and S-100 protein." (PMID 22192457, 2011). "Anti-vimentin antibody treatment inhibited subcutaneous tumor xenograft growth and tumor blood vessel density in mice, suggesting that vimentin is localized to the cell surface in tumor endothelial cells." (PMID 22216242, 2011). "In contrast to benign breast tissue, a statistically significant association was observed between vimentin-positive and α-SMA-positive fibroblasts in the tumour microenvironment at both the primary and metastatic sites." (PMID 21897388, 2011). "Data indicate that surface vimentin is preferentially expressed on tumor endothelium compared to healthy vasculature." (PMID 24212937, 2011). "Analysis of NRP2 transfected cell lines and NRP2 expressing xenografts established that NRP2-expressing tumor cells displayed an immunohistochemical phenotype of EMT characterized by the loss of E-Cadherin and an increase of vimentin expression." (PMID 21747928, 2011). "Pancreatic neoplastic tissues showed a three-fold higher expression of vimentin than neoplasms of other origins (lung, colon and ovary), and had higher levels of an isoform with demonstrable immunogenicity." (PMID 21448168, 2011). "Vimentin expression appeared to be dichotomous with high and intermediate staining populations of cells for each tumor type." (PMID 24212937, 2011). "E-cadherin expression was higher in the tumor center than in the tumor periphery, whereas L1CAM and vimentin were expressed at the tumor-stroma interface." (PMID 21985405, 2011). "Using double-immunostaining we found different populations of cells within the tumor stroma i.e. vimentin-positive cells, as well as cells positive for both vimentin and desmin and some cells staining positive for desmin only." (PMID 22141345, 2011). "Desmin and vimentin double immunostaining was performed on 17 tumor samples to assess co-localisation." (PMID 22141345, 2011). "By univariate survival analysis, patients’ outcome was correlated with poor histological differentiation, positive tumour resection margins, the presence of lymph node metastases, increased tumour size and tumour epithelial vimentin expression." (PMID 21448168, 2011). "The selected candidate samples were subsequently stained using an anti-multi-cytokeratin antibody to identify tumor cells within tissue sections and an anti-vimentin antibody to identify the stromal compartment." (PMID 21611158, 2011). "With regard to therapeutic efficacy and targeting, glioma patients showed reduced tumor growth after intravenous treatments with the vimentin-specific antibody CLN-IgG." (PMID 24212937, 2011). "The immunoprofile of these tumours is characterized by simultaneous positivity for S-100 protein, vimentin and EMA." (PMID 21320334, 2011). "We suggest that the physiological relevance of these results is supported by findings that vimentin and CD44 are up-regulated on tumor endothelial cells, whereas vimentin has been proposed as a potential anti-angiogenesis target." (PMID 22216242, 2011). "Expression of proteins that are characteristic of mesenchymal cells (e.g. vimentin, FSP1/S100A4, SNAI1, SNAI2, and stromelysin-3) and loss of epithelial markers (e.g. E-cadherin) correlates with tumor progression and poor prognosis." (PMID 21966391, 2011). "Immunohistochemically, the stromal cells of the tumor show strong positivity for vimentin and variable positivity for desmin, α-smooth muscle actin, and CD34." (PMID 21143833, 2010). "The candidate substrates identified in our analysis (e.g. p120, integrin β4, plakophilin 3, STAT3 and vimentin) will inform future studies addressing the mechanisms involved in CSF-1R-induced tumor progression." (PMID 21049007, 2010).
tumor (continued). "An important finding of our study was that, according to immunofluorescence assay, a fraction of fibroblast-like vimentin-positive cells in some tumour and normal stromal cell cultures expressed an epithelial marker – cytokeratins." (PMID 20407446, 2010). "Gene expression profiles assessed from laser capture-micro-dissected GBM cells have shown high levels of vimentin in the tumor core." (PMID 21317457, 2010). "Immunohistochemically the tumour cells showed an expression of Vimentin and CD117, a focal expression of CD34, smooth-muscle-actin (not shown) and a nuclear expression of the proliferation-associated Ki-67-antigen in approximately 5-10% of the tumour cells." (PMID 20515511, 2010). "This was accompanied by an increased expression of E-cadherin and Keratin-18 and a decreased expression of vimentin in tumor tissues." (PMID 20573255, 2010). "AE1/AE3 produced weak to moderate staining and Vimentin was positive in ~90% cells in the sarcomatoid component of the primary tumor." (PMID 20181105, 2010). "That suggests that vimentin should play an important role in tumor progression and serve as a potential biomarker for the metastasis." (PMID 20701774, 2010). "Double immunofluorescence and western blot analysis of differentiation markers revealed a fraction of vimentin/cytokeratin double-positive cells in some established tumour and normal cultures." (PMID 20407446, 2010). "Both the elbow emboli with the extratumoral foci of FRMS and the intratesticular tumor were positive for Myogenin, MyoD1, Vimentin and Desmin." (PMID 20701800, 2010). "Striking features of these tumours are the diffuse proliferation pattern of the undifferentiated tumour cells and the positive immunoreactivity for vimentin, S-100, and neuron-specific enolase." (PMID 20051954, 2010). "With a structural function of vimentin in the cytoskeletal scaffolding, it can be assumed that vimentin plays a key role in the process of tumor cell migration or motility." (PMID 20169076, 2010). "The tumor was identical immunohistochemically to a low grade fibromyxoid sarcoma with strong positivity to vimentin." (PMID 19956483, 2009). "By immunohistochemistry, the tumour was positive for cytokeratins, smooth muscle actin, vimentin, laminin, collagen type IV, CD8, and CD68." (PMID 19918462, 2009). "In general, acidophilic granular cytoplasm and immunoreactions for vimentin, S100 protein, and neuron-specific enolase are important points in this tumor." (PMID 27956961, 2009). "For patients with 'vimentin or CK5/6, 14, 17-positive' tumours, 5-year estimated survival rate was 78.6%, whereas for patients with 'vimentin, or CK5/6, 14, 17-negative' tumours it was 58.3% (log-rank p = 0.227)." (PMID 19695088, 2009). "The appearance of other populations, e.g. fibroblasts or myoepithelial cells remained undetectable and further characterization of HBCEC revealed a predominant co-expression of cytokeratins and vimentin within the tumor-derived cells." (PMID 19751512, 2009). "Taken into consideration a strong positive correlation between EGFR and vimentin expression, we have taken an effort to construct an immunopanel defining basal-type tumours as triple negative tumours that are vimentin-positive or basal cytokeratin-positive." (PMID 19695088, 2009). "PIA treatment induced the expression of E-cadherin and β-catenin, reduce that of Vimentin, restored their epithelial morphology of a polygonal shape, and reduced tumor cell migration in KB and KOSCC-25B cells, which was the corresponding feature of MErT." (PMID 19243631, 2009). "In our study, there was a statistically significant correlation between vimentin expression and poor differentiation of tumours (G3 cancers) both in all patients and in the triple negative group." (PMID 19695088, 2009). "On the contrary, there was an insignificant tendency towards better prognosis when basal keratins or vimentin were detected in a primary tumour." (PMID 19695088, 2009).
tumor (continued). "Immunohistochemistry reveals that the tumor is typically keratin-, vimentin-, pancreatic polypeptide-, and chromogranin-positive, with a lesser number of tumors proving to be neuron-specific-enolase (NSE), synaptophysin-, serotonin- and S-100 protein-positive." (PMID 20111612, 2009). "There was also a statistically insignificant but quite obvious tendency towards a relationship between vimentin and cyclin E. Vimentin-positive tumours more frequently expressed cyclin E (p = 0.058)." (PMID 19695088, 2009). "Among 38 vimentin-positive tumours, 31 were ER-negative and 31 were PgR-negative, whereas 7 were ER and PgR-positive (p < 0.001)." (PMID 19695088, 2009). "High expression of NF-κB p105 and low expression of vimentin in tumour epithelial cells are independent predictors of better survival in primary NSCLC." (PMID 18854838, 2008). "In multivariate analyses, the tumour epithelial cell expression of NF-κB p105 (P=0.0001) and vimentin (P=0.005) and the stromal cell expression of NF-κB p105 (P=0.007) and Par6 (P=0.0001) were independent prognostic factors for DSS." (PMID 18854838, 2008). "Aberrant expression of vimentin in tumours and transformed cell lines has been correlated with increased motility, invasive behaviour and poor prognosis." (PMID 18212748, 2008). "This tumour can be confused with chondrosarcoma but it is characterized by positive immunohistochemistry to vimentin, S-100 protein, and epithelial markers, namely keratin and EMA (Epithelial Membrane Antigen)." (PMID 18279530, 2008). "Even among the patient group with poorly differentiated tumours, high tumour epithelial cell vimentin expression tended to correlate with poor survival (P=0.08)." (PMID 18854838, 2008). "Consistently, this tumor was also positive for protein expression of a mesenchymal marker, vimentin." (PMID 18394172, 2008). "Tsai WC showed that actin and vimentin expression in breast phyllodes tumors correlates with tumor grades of the WHO grading system." (PMID 18847500, 2008). "Recently, it was reported that the presence of vimentin-positive tumour cells mainly in fibrotic areas is consistent with other studies that have shown a correlation between tumour fibrosis and epithelial–mesenchymal transition." (PMID 18212748, 2008). "Expression of vimentin and Par6 in tumour epithelial cells correlated significantly (r=0.2, P<0.001), as did vimentin and tumour differentiation (r=−0.1, P=0.01)." (PMID 18854838, 2008). "Histologically, the tumor cells are polygonal with abundant eosinophilic cytoplasm and eccentric nuclei and on immunostaining, these cells are variably positive for desmin, vimentin, GFAP, CK, EMA, SMA and synaptophysin." (PMID 18439235, 2008). "Immunohistochemically, the tumour cells express vimentin, desmin, smooth muscle actin, and muscle specific actin, but not cytokeratin, neurofilament, or glial fibrillary acidic protein." (PMID 19068127, 2008). "If indeed the increased vimentin is caused by this group of cells, our results would advocate that TIL suppress the immune response against the tumour." (PMID 17325702, 2007). "Akin to our in vitro findings, these tumours largely express cytokeratin and lack vimentin expression." (PMID 17406365, 2007). "The tumor was strongly positive for vimentin and different cytokeratins including the squamous differentiation marker CK5/6." (PMID 17212821, 2007). "Immunohistochemistry (IHC) showed diffuse co-expression of epithelial markers i.e. cytokeratins (CK, HMWCK, CK7) and EMA along with a mesenchymal marker i.e. vimentin in the tumor cells." (PMID 17324295, 2007). "We found that vimentin expression in the tumour stroma was useful in identifying CRC patients with a poor prognosis." (PMID 17325702, 2007). "Increased stromal vimentin expression indicated a dynamic change in the tumour stroma during tumour progression." (PMID 17325702, 2007).
tumor (continued). "To molecularly determine if these tumours reverted to a more epithelial phenotype, we stained for the epithelial marker cytokeratin 18 and the mesenchymal marker vimentin." (PMID 17406365, 2007). "Higher expression of vimentin in stromal cells and also polymorph nuclear cells and mononuclear cells, which were frequently found within the lobes of tumor strongly, reacted with vimentin antibodies." (PMID 17880731, 2007). "For stage II tumours, the disease-free survival rate for the high vimentin expression group was 71.4% compared with 92.3% in the low-expression group (P=0.029)." (PMID 17325702, 2007). "Vimentin expression was significantly higher in the stromal compartment in both normal tissue (P<0.05) and tumour tissue (P<0.001)." (PMID 16465195, 2006). "Using 2-D PAGE, we examined the expression of the different vimentin isoforms in a variety of tissues and tumor types." (PMID 18769604, 2006). "They concluded that if a tumor exhibited strong positive staining with vimentin and ER, it was almost certainly of endometrial origin." (PMID 16409624, 2006). "Previous publications have demonstrated an unexpected coexpression of the intermediate filament proteins cytokeratins and vimentin in various tumour cells, which seems to correlate with their metastatic potential." (PMID 14735193, 2004). "The tumour cells were positive for vimentin and smooth muscle actin, butnegative for desmin, NSE, Factor VIII, chromogranin, cytokeratin." (PMID 18521375, 2003). "All the tumours formed by the injection of c-erbB-2-expressing cells showed the same features except that they were positive for vimentin." (PMID 14676809, 2003). "Histologically, tumours induced by co-inoculation of tumour cells and fibroblasts contained more stromal structures including vimentin-positive cells, fibronectin and interstitial collagens." (PMID 8217606, 1993). "High Vimentin was associated with lower median OS (17.0 ± 4.4 vs. 25.8 ± 2.3 months, p = 0.037) and DFS (8.6 ± 1.2 vs. 13.0 ± 2.3 months, p = 0.014), compared to low Vimentin, and it was correlated with higher tumor grade (p = 0.028) and metastasis rate (p = 0.032)." (PMID 42070977, 2026). "We detected a decrease of human vimentin abundance consistent with the decrease in tumor size." (PMID 41181988, 2026). "Numerous studies have demonstrated ZEB1 directly regulates the expression of Vimentin directly binding to the promoter region of Vimentin and inducing its transcription, resulting in the acquisition of a mesenchymal phenotype and enhancing tumor cell invasiveness." (PMID 41481650, 2026). "Moreover, quantitative PCR on xenograft tumor samples revealed that CTGF, ZEB1, and vimentin expression exhibited the same pattern as tumor growth, but E-cadherin expression had the opposite effect." (PMID 41216500, 2026). "Indeed, WISP1 treatment induced a partial EMT phenotype characterized by reduced membrane E-cadherin, increased fibronectin, and elevated vimentin, consistent with migratory yet adaptable tumor cell states." (PMID 41597235, 2026). "HNF4α exerts an inhibitory effect on EMT through its effect on the Wnt/β-catenin signaling pathway via the upregulation of E-cadherin, along with the downregulation of β-catenin and Vimentin, which collectively contribute to the suppression of tumor growth and metastasis in HCC." (PMID 40277924, 2025). "Finally, in the SSC, E-cadherin expression was markedly reduced, remaining detectable only in isolated residual clusters of epithelial cells, whereas Vimentin expression was increased in tumor cells and, more prominently, in the stromal compartment." (PMID 41155492, 2025). "In addition, miR-375 has also been shown to reduce tumor invasiveness by regulating proteins such as vimentin and L-plastin, which are crucial for cell migration." (PMID 40076805, 2025).